INS (insulin)
Diseases named in the same sentence as INS in open-access papers (continued):
Sharing a sentence is not in itself a finding about the gene and the disease.
Glucose intolerance (continued). "Affected DEK rats were previously shown to exhibit severe glucose intolerance, no insulin secretion in response to glucose loading, and loss of β cells." (PMID 33945582, 2021). "Moreover, only these recuperated IUGR mice showed the modified expression of genes related to the insulin/insulin-like growth factor signaling pathway at 3 months of age, along with glucose intolerance at 9 months of age." (PMID 33915805, 2021). "However, when challenged to diabetogenic conditions, the mice developed glucose intolerance with lower fasting serum insulin levels." (PMID 34685781, 2021). "It has been reported that this difference can lead to subtle yet relevant phenotypic differences, comprising higher blood glucose concentrations, glucose intolerance, lower insulin secretion and lower oxygen consumption in C57BL/6 J, possibly due to the Nnt mutation." (PMID 33790318, 2021). "Alternatively, if endogenous insulin production is reduced, but insulin sensitivity increased in PEA-15−/− mice, this could also result in modest glucose intolerance despite apparent improved insulin sensitivity." (PMID 33772049, 2021). "Interestingly, aged p110αD933A/WT mice are protected from age-related reductions in insulin sensitivity, glucose intolerance and fat accumulation, and exhibit a slightly extended lifespan in male mice (by 6% compared to wt littermates." (PMID 33431926, 2021). "However, 2-month-old SIRT2-KO male rats exhibited glucose intolerance and decreased insulin secretion in response to glucose challenge compared with WT rats." (PMID 33754030, 2021). "In the gene-level analyses, we first tested diet-level changes between groups and found that both WT and ChemR23 KO obese mice had dysregulated pathways related to insulin signaling, glucose intolerance, hepatic steatosis, and NAFLD compared to lean WT and ChemR23 KO controls." (PMID 35004828, 2021). "Since a disrupted collective activity is an important and possibly early contributor to impaired insulin secretion and glucose intolerance, it is of utmost importance to understand possible effects of NMDA receptor inhibition on beta cell functional connectivity." (PMID 33974632, 2021). "Conversely, in livers of IL-6 knockout mice, which develop glucose intolerance without a change in insulin sensitivity, hepatic insulin clearance is reduced, which is associated with reductions in the levels of IDE mRNA, protein and activity." (PMID 33477364, 2021). "However, the GABAB-R agonist baclofen is known to impair glucose intolerance and diminish insulin secretion in mice which is counter to our observations that lesogaberan treatment promoted normoglycemia." (PMID 33418884, 2021). "However, in this study, women with severe glucose intolerance had only a partial improvement and still needed insulin therapy." (PMID 34071548, 2021). "In addition, another mouse study showed glucose intolerance and impaired insulin secretion in 8-week-old male offspring." (PMID 33789751, 2021). "Glucose intolerance can arise from impaired β-cell insulin secretion or insulin resistance." (PMID 33772108, 2021). "Furthermore, we also observed that maternal SE would induce glucose intolerance together with reduced plasma insulin level, which is consistent with the previous study in both human and mouse models." (PMID 34276421, 2021). "Notably, 8-weeks-old offspring of obese dams continued to exhibit a similar pattern of sex-differences in glucose intolerance and decreased islet insulin secretion." (PMID 34108935, 2021). "Such an increase in autophagy is required for the compensatory increase in β cell mass and survival of insulin‐producing cells, as witnessed by the fact that genetic ablation of Atg7 in β cells promotes their demise, leading to impaired insulin production and glucose intolerance." (PMID 34459017, 2021).
Glucose intolerance (continued). "Reduced insulin sensitivity with increased glucose production and inhibition of the production and secretion of insulin by pancreatic β-cells are considered to be the key mechanism of glucose intolerance." (PMID 34830886, 2021). "The glucose intolerance in HIF1αKOMBH mice may be due to higher insulin secretion baseline in these mice, which leads to insulin deficiency when facing glucose challenge." (PMID 34733235, 2021). "Unlike males, TCDD did not impact insulin sensitivity or islet composition in females, but did cause transient glucose intolerance 4 weeks post-exposure." (PMID 31996693, 2020). "This lowering of AKT phosphorylation in the liver suggests reduced insulin signaling, which could promote glucose intolerance as seen in the glucose tolerance test." (PMID 32842637, 2020). "We also observed a glucose intolerance and reduced insulin sensitivity in mice overexpressing RAGE." (PMID 32936538, 2020). "In addition, serotonergic drugs, including fenfluramine, fluoxetine and sertraline, improved glucose intolerance and insulin sensitivity in obese and diabetic rats or humans." (PMID 33187155, 2020). "Compared with the MOD group, the EMP group showed a significant decrease (p < 0.05) in the AUC-GTT and AUC-ITT, indicating that EMP could ameliorate glucose intolerance and increase insulin sensitivity." (PMID 32256445, 2020). "Moreover, mice harbouring paternally-truncated Kcnq1ot1 displayed glucose intolerance and defects in insulin secretion." (PMID 33628198, 2020). "Deletion of Insm2 in mice resulted in reduced insulin secretion and glucose intolerance." (PMID 32511227, 2020). "In other words, our results confirm that mirtazapine can retard body weight gain and reduce food intake, in addition to reducing glucose intolerance, serum insulin levels, daily food efficiency, adipocyte size, liver and epididymal fat pad weights, and fatty liver scores." (PMID 32824002, 2020). "In addition to that, ginsenoside Rb1 also relieved glucose intolerance induced by STZ injection by enhancing insulin sensitivity." (PMID 32550230, 2020). "Mild/Moderate exercise has been shown to lower blood pressure, lower total serum cholesterol, maintain a healthy LDL/HDL ratio, improve body composition, protect myocardial function, prevent glucose intolerance, improve autonomic nervous system and increase insulin sensitivity." (PMID 32673347, 2020). "However, SkM-specific overexpression of miR-17 resulted in a significant improvement in higher blood glucose, glucose intolerance, and insulin insensitivity, and moreover, rescued the SkM from the suppression of insulin-stimulated pAkt and mGlut4." (PMID 32802189, 2020). "In 0.4 mg/kg F1 insulin reduction was less pronounced, and glucagon was decreased, which could explain the less marked glucose intolerance." (PMID 33093533, 2020). "However, when fed with HFD mice with PKD1 deletion in β-cells were characterized by glucose intolerance and impaired glucose-induced insulin release." (PMID 32466765, 2020). "These suggest that elevated chemerin in those with glucose intolerance may be the compensatory consequence to stimulate insulin secretion." (PMID 32561824, 2020). "The phenocopies of GK rats are characterized by glucose intolerance and impaired insulin secretion." (PMID 33139642, 2020). "Thus, we have found that mice carrying a Vav2 mutant protein with reduced catalytic activity exhibit impaired IGF1- and insulin-mediated PI3Kα signaling, reduced muscle mass, and increased glucose intolerance." (PMID 33199701, 2020). "As PSO has been reported to play a role in insulin and glucose regulation, we sought to investigate whether the supplementation of PSOn modifies the glucose intolerance induced by the HFD." (PMID 32943651, 2020).
Glucose intolerance (continued). "• Obesogenic impact of early and intrauterine exposure to BPA.• Glucose intolerance and decreased insulin sensitivity were observed in young and adult mice perinatally exposed to BPA.• Perinatal BPA exposure may also result in a loss of intestinal barrier." (PMID 33329442, 2020). "In our study, succinate was negatively correlated with the area under the curve (AUC) during OGTT and was positively correlated with the drop rate in glucose during IPITT (AUC below baseline), which are indicators of glucose intolerance and insulin sensitivity, respectively." (PMID 32932138, 2020). "In addition, it is proposed that phenolic acids regulate postprandial glycemia and reduce glucose intolerance by facilitating insulin response and stimulating glucose-dependent insulinotropic polypeptide release and glucagon-like peptide-1 (GLP-1)." (PMID 33457416, 2020). "Reduced plasma insulin in F1 after exposure to 0.1 mg/kg DE-71 may contribute, in part, to the pronounced glucose intolerance seen in this group." (PMID 33093533, 2020). "PASK-deficient mice have better insulin sensitivity and no glucose intolerance, as confirmed by a normal HOMA-IR index." (PMID 31974316, 2020). "Importantly, PKCθ mediates palmitic acid-induced suppression of insulin signaling in the arcuate nucleus promoting body weight gain and glucose intolerance in mice fed HFD." (PMID 32466765, 2020). "Thus, Nnt, which influences β cell insulin secretion in the pancreas, is one of the responsible proteins for the impaired insulin secretion and glucose intolerance in the C57BL/6J strain." (PMID 33053789, 2020). "Moreover, the authors found that KHFAC effects were reversible, as upon cessation of electrical modulation insulin resistance and glucose intolerance returned to normal values within 5 weeks." (PMID 33353562, 2020). "As anessential molecule in insulin signaling, the dysfunction of IRS-1 could decrease downstream insulin effects, thereby contributing to glucose intolerance." (PMID 31195990, 2019). "Glucose intolerance and decreased insulin sensitivity are hallmarks of the obese state." (PMID 31134094, 2019). "Because adiponectin signaling is involved in insulin sensitization, the observed reduction in adiponectin in this work may be a reason for the observed glucose intolerance." (PMID 30728429, 2019). "This may explain the lower level of insulin sensitivity and secretion, as well as all levels of glucose intolerance." (PMID 31141980, 2019). "Insulin resistance (due to mTORC2 deactivation) in addition to decreased insulin secretion (due to mTORC1 deactivation) may contribute to glucose intolerance." (PMID 31406105, 2019). "Patients whose glucose intolerance improved after surgery had shorter disease durations, lower insulin sensitivities, higher IR, and higher FINS, FCP, HOMA-β, and disposition indices, indicating that β-cell functioning was partially preserved in the improved group." (PMID 31736874, 2019). "However, measures of glucose homeostasis were also perturbed after three days high-fat diet, characterised by raised blood glucose and insulin, and glucose intolerance." (PMID 29171775, 2019). "We next examined the hypothesis that genetic reconstitution of hepatic RGS16 in the context of Arg2 overexpression would reverse the improvements in hepatic steatosis, inflammation and insulin and glucose intolerance observed in Arg2-treated db/db mice." (PMID 30962478, 2019). "Adipsin knock-out mice were shown to develop glucose intolerance due to decreased insulin production, while administration of adipsin in diabetic mice resulted in a boost in insulin secretion and consequent decreased glucose levels, through signaling pathways downstream of C3a receptors in β-cells." (PMID 31404407, 2019). "Moreover, the obese groups with glucose intolerance or T2D exhibited, as expected, increased glucose and insulin levels 2 h after the OGTT (P<0.05 for both)." (PMID 30897065, 2019).
Glucose intolerance (continued). "Maternal hypothyroidism results in impaired pancreatic insulin synthesis and pancreatic cell proliferation in neonatal offspring and subsequent glucose intolerance in young offspring, which may be related to TRβ gene downregulation in the pancreas." (PMID 30918900, 2019). "Pancreatic aberrances, e.g., glucose intolerance, reduced insulin release and inflammation." (PMID 30804742, 2019). "Decreased GRK2 levels in global GRK2+/− mice prevent the development of an insulin resistant and obese phenotype in terms of body weight gain, glucose intolerance, and insulin insensitivity in skeletal muscle and liver, thus maintaining glucose homeostasis and favoring energy expenditure." (PMID 31752326, 2019). "During the last few decades, emerging research has focused on the role of gut microbiota in metabolic diseases and showed that gut microbiota dysbiosis was intertwined with various disorders, such as glucose intolerance, insulin sensitivity and disturbances of serum lipid profiles." (PMID 31417434, 2019). "In insulin-producing β cells, excess autophagy degrades insulin granules, resulting in decreased insulin contents and systemic glucose intolerance, whereas in insulin-responsive cells, activating autophagy decreases endoplasmic reticulum (ER) stress and improves insulin sensitivity." (PMID 31511772, 2019). "However, the IVGTT allowed us to measure insulin secretion and to show that glucose intolerance in active acromegaly is mostly dependent on insulin secretion and not on insulin sensitivity." (PMID 31620090, 2019). "Furthermore, consistent with the observed glucose intolerance, the response in blood glucose concentration to an intraperitoneal injection of insulin was also impaired." (PMID 31399502, 2019). "Given the low insulin secretion of these patients, this confirms the hypothesis that in active acromegaly, glucose intolerance is driven mainly by the inadequate insulin secretion in the face of reduced insulin sensitivity." (PMID 31620090, 2019). "Moreover, glucose tolerance as well as insulin tolerance tests further confirmed the increase of glucose intolerance and insulin insensitivity after fat removal." (PMID 31780791, 2019). "We propose that TRPV1 could be a promising therapeutic target in T2DM by improving glucose intolerance and correcting dysfunctional insulin secretion." (PMID 31344877, 2019). "Azilsartan improves glucose intolerance and insulin sensitivity in animal models." (PMID 30943275, 2019). "Overall, this suggests that the sample population that participated in this study may have had some level of glucose intolerance and possibly a reduction in insulin sensitivity." (PMID 31689951, 2019). "Therefore, 12 weeks of feeding with the HF diet was deemed sufficient to induce glucose intolerance and insulin insensitivity, prior to microbial interventions." (PMID 31704943, 2019). "In the present study, we found that a 4-week consecutive exposure to TBT (0.25 mg/kg) in mice caused an increase in fasting blood glucose, a decrease in plasma insulin, and an elevation in glucose intolerance accompanied by a significant increase of plasma lipid peroxidation." (PMID 29636531, 2018). "Because skeletal muscle atrophy can cause physical decline such as impaired cytokine and insulin signaling that may result in glucose intolerance, we speculate that stratification by muscle mass may reflect physical condition." (PMID 29789798, 2018). "Furthermore, Y1lox/lox/INS2cre/+ mice exhibit significantly increased blood glucose levels and developed glucose intolerance, while glucose-stimulated insulin secretion is significantly elevated in vivo." (PMID 30177746, 2018). "Also, Fam3b overexpressing mice displayed decreased insulin secretion and increased glucose intolerance." (PMID 30687391, 2018). "Indeed, mice lacking Cdk2 are viable and targeted Cdk2 deletion in the pancreas induces glucose intolerance primarily by affecting glucose-stimulated insulin secretion." (PMID 30300385, 2018).
Glucose intolerance (continued). "Early chronic intervention with the GLP-1 receptor agonist liraglutide starting before the onset of metabolic symptoms prevented the development of glucose intolerance, improved insulin and glucagon secretion control, reduced ER stress and inflammation in Langerhans islets in Wfs1 mutant rats." (PMID 29976929, 2018). "In our IGT and type 3c diabetic PPP, as in a previous cohort of type 2 diabetic individuals undergoing surgery for pancreatic cancer, glucose intolerance correlated with altered hepatic function and insulin resistance secondary to compression of the biliary duct by the pancreas head." (PMID 29185012, 2018). "Beta-cell specific ZnT8 knock out mice display glucose intolerance, abnormal β-cell morphology, reduced islet insulin processing, a reduction in the total number of granules, and an increase in empty atypical granules suggesting that insulin crystallization and packaging is compromised." (PMID 29373583, 2018). "Interestingly, maternal folate supplementation during pregnancy counteracted the pancreatic effects of BPA (which included disrupted insulin secretion, impaired beta cell morphology, and glucose intolerance) in adult rat offspring." (PMID 30233498, 2018). "Instead, β cell Nnat deficiency in mice causes loss of appropriate insulin secretion control, with complete absence of glucose-evoked insulin release and glucose intolerance under conditions of nutrient excess." (PMID 29864031, 2018). "In mice, loss of melatonin or serotonin signaling leads to glucose intolerance and insulin resistance, with consequences for blood glucose and insulin concentrations in both the non-pregnant and pregnant state." (PMID 30174608, 2018). "It seems to contribute to glucose intolerance and to reduce insulin sensitivity." (PMID 29915558, 2018). "Insulin sensitivity and glucose intolerance were greatly deteriorated in DIO rats." (PMID 30425749, 2018). "Considering glucose intolerance may anticipate the elevation in blood glucose, we assessed the glucose tolerance on the 8th, 22nd, and 36th days, and the insulin sensitivity on the 9th, 23rd, and 37th days of the experimental protocol." (PMID 30686986, 2018). "Furthermore, there are reported cases of glucose intolerance and low insulin levels in patients with carcinoid syndrome, characterized by excessive systemic 5HT levels." (PMID 28129327, 2017). "Moreover, glucose intolerance improved as evidenced by the oral glucose tolerance test, and fasting plasma insulin levels decreased in both types of Zn complex-treated mice." (PMID 29215553, 2017). "STAT3 deficiency in the pancreas causes incomplete development of the pancreatic microvasculature, which may restrict insulin transportation, leading to glucose intolerance and a defect in insulin secretion in vivo." (PMID 28978186, 2017). "Multivariate regression test showed that risk factors associated with persistent glucose intolerance 6–12 weeks postpartum were inclusive of earlier diagnosis of GDM, use of insulin or metformin for management of GDM, FPG ≥ 100 at the time of OGTT, and systolic blood pressure." (PMID 28491872, 2017). "In light of the recognized benefits of physical activity on reducing the incidence of T2D development in people with glucose intolerance, further study of how different types of exercise modes influence membrane and cytoskeletal aspects of insulin action are warranted." (PMID 28811359, 2017). "In addition, MSCs also improve inflammation-related glucose intolerance in T2D rats, further certifying their beneficial role in regulating insulin sensitivity in vivo." (PMID 29096724, 2017). "Overexpression of a dominant-negative version of Raptor in the liver improved insulin sensitivity, whereas inhibition of mTOR by rapamycin reduced the production and release of insulin by pancreatic islets, leading to hypoinsulinemia and glucose intolerance." (PMID 28795262, 2017).